PGK1 (phosphoglycerate kinase 1)
Diseases named in the same sentence as PGK1 in open-access papers (continued):
Sharing a sentence is not in itself a finding about the gene and the disease.
tumor (continued). "Moreover, using TCGA data, we calculated the enrichment fraction of each sample in the tumor proliferation pathway and demonstrated that PGK1 was associated with the tumor proliferation pathway." (PMID 39315723, 2024). "The genes PFKP, PFKM, and PGK1 were associated with oncogenes that could reinforce the Warburg effect and tumor progression." (PMID 39684297, 2024). "Similarly, high PGK1 expression was positively associated with tumor mutational burden (TMB), a promising indicator to differentiate responders to immune checkpoint inhibitors." (PMID 34668665, 2021). "Associations of PGK1 with immunological features in the tumor microenvironment (immune checkpoints, immune response predictors (tumor mutation burden (TMB) and microsatellite instability (MSI)), and tumor-infiltrating immune cells) were systematically analyzed." (PMID 34790279, 2021). "Tumor specific variants and the mRNAs of housekeeping gene PGK1 were detected in cfDNA and RNA isolated directly from chips in PCR, NGS, and RT-PCR assays, demonstrating that high-quality material can be isolated from donor samples using the isolation workflow." (PMID 33224932, 2020). "PGK1 is a key enzyme in glucose metabolism and is involved in various biological activities, including chemotherapy resistance, angiogenesis, epithelial–mesenchymal transition, autophagy initiation, mitochondrial metabolism, and other processes associated with tumor development." (PMID 40016971, 2025). "Additionally, PGK1 is associated with chemotherapy resistance and prognosis in tumour patients." (PMID 37723547, 2023). "The loss of PGK1 could drastically suppress the proliferation of tumor cells." (PMID 38098044, 2023). "Taken together, this study highlighted PGK1 as a pivotal regulator of tumor immunobiology and provided novel insights into combination immunotherapy for HCC." (PMID 42183839, 2026). "This study found that HCC cell-intrinsic PGK1 contributed to tumor progression through inhibiting CD8+ T cell-mediated antitumor immunity." (PMID 42183839, 2026). "ACT001 inhibits the malignant progression of SCLC by suppressing lactate production, modulating macrophage polarization, and restraining tumor metastasis through PGK1 targeting." (PMID 40016971, 2025). "PGK1 expression in tumour tissues were higher than non‐tumour tissues from GSE161533, GSE44021, GSE23400, GSE46452, GSE37203, and TCGA database." (PMID 40534132, 2025). "Our study revealed that the expression of the key glycolysis gene PGK1 negatively correlates with the sensitivity of tumor cells to lapatinib." (PMID 40786054, 2025). "Previous studies have revealed a positive correlation between O-GlcNAcylation and tumor growth via the stabilization of target proteins such as phosphoglycerate kinase 1 (PGK1) and the ribosomal receptor for activated C-kinase 1 (RACK1)." (PMID 39984622, 2025). "In conclusion, this study reveals that the natural product derivative ACT001 exhibits potential cytotoxicity against SCLC cells and regulates tumor glycolysis and anti‐tumor immunity by targeting PGK1." (PMID 40016971, 2025). "The polarized M2 macrophages can increase phosphoglycerate kinase 1 (PGK1) phosphorylation in tumor cells, mediated by 3-adenosine phosphate-dependent protein kinase 1 (PDPK1) in tumor cells by secreting IL-6." (PMID 40297580, 2025). "This review discusses how epigenetic mechanisms, including m6A methylation and ceRNA networks involving circRNAs and microRNAs, modulate key glycolytic enzymes such as PKM2, HK2, and PGK1, thereby promoting tumor growth, metastasis, and chemoresistance." (PMID 40977684, 2025). "These experiments demonstrate that ACT001 inhibits tumor metastasis and lactate production by targeting PGK1." (PMID 40016971, 2025). "PGK1 catalyzes the first ATP production step in glycolysis, which is related to tumor cell metabolism and cancer development." (PMID 41426311, 2025).
tumor (continued). "Together, these findings indicate that PGK1 function can be regulated by different PTMs in response to various stimuli or the tumor microenvironment, which subsequently promote different aspects of cancer properties." (PMID 41184227, 2025). "This phosphorylation enhances PGK1-catalyzed glycolysis by altering substrate affinity, thereby increasing tumor energy supply." (PMID 40297580, 2025). "In vivo, xenograft model indicated that knockdown of MYH9 significantly inhibited the PGK1‐mediated tumour growth and the expression of Snail, SOX2 and β‐catenin." (PMID 40534132, 2025). "To validate these findings, we performed IHC staining on 60 pairs of primary PDAC tumor specimens and their matched normal tissues using an anti-PGK1 antibody." (PMID 41213904, 2025). "In vivo and in vitro experimental analyses revealed that PGK1 promoted ESCC cell tumour stemness and EMT both in vivo and in vitro." (PMID 40534132, 2025). "Approaches that inhibit TRIM8-mediated K63 ubiquitination and PGK1-regulated glycolysis likely increase the efficacy of tumor angiogenesis treatment." (PMID 41184227, 2025). "TRIM8 and its induced K63 ubiquitination promote the interaction of PGK1 with ACAT1, thereby facilitating PGK1 acetylation and downstream glycolysis for lactate accumulation and tumor angiogenesis." (PMID 41184227, 2025). "At the same time, PGK1, a key glycolytic enzyme, is subjected to high succinylation at the K191 and K192 sites, which in turn enhances glycolysis in tumor cells and aids tumor growth." (PMID 40867281, 2025). "PGK1, a key enzyme in the glycolytic pathway, generates ATP and maintains energy homeostasis in tumor cells." (PMID 41213904, 2025). "Recent research has demonstrated that PGK1 is aberrantly activated in neoplastic cells, functions as a pivotal oncogenic factor in various tumour types." (PMID 40534132, 2025). "Research on PGK1 has primarily focused on oncology, with previous data indicating its involvement in tumor development and progression." (PMID 40177399, 2025). "Functional experiments demonstrated that knockdown of PGK1 or PCMT1 inhibited tumor cell proliferation and reduced the phosphorylation levels of mTORC, P70S6K, S6, and AKT, indicating suppression of the PI3K/AKT/mTOR pathways." (PMID 40204712, 2025). "Elevated levels of PRMT1 and methylated PGK1 correlate with advanced tumour stages and poorer survival rates in CRC patients." (PMID 41154605, 2025). "Further investigation into the mechanisms regulating PGK1 function is required to better understand how PGK1 signaling is maintained in tumor cells." (PMID 41213904, 2025). "Second, most experiments were conducted in vitro, and the impact of AAMP‐mediated PGK1 phosphorylation on tumor growth has yet to be validated in vivo using animal models." (PMID 40529105, 2025). "High PGK1 expression, male gender, poor differentiation, large tumour size, positive pathology lymph node, and high TNM stage were found associated with worse overall survival in univariate analysis." (PMID 40534132, 2025). "The findings demonstrated that, in contrast to non‐metastatic tumours, both PGK1 and MYH9 were substantially expressed in metastatic tissues, and in recurrent tissues compared to primary lesions." (PMID 40534132, 2025). "Tumour sphere formation assays demonstrated that the hypoxia‐induced enhancement of ESCC cells stemness was abolished following PGK1 knockout." (PMID 40534132, 2025). "Our findings uncover a novel mechanism by which TRIM8 promotes tumor angiogenesis by regulating tumor cell metabolism and implicates a therapeutic potential to disrupt the connection between metabolism and angiogenesis by inhibiting PGK1 K63 ubiquitination." (PMID 41184227, 2025). "Transwell assays revealed that hypoxia's promotion of tumour migration ability was abrogate by PGK1 knockdown." (PMID 40534132, 2025). "In our study, we found PGK1 was upregulated in advanced tumour tissues which underwent much more hypoxia and HIF‐1α expression." (PMID 40534132, 2025).
tumor (continued). "In PC, the lncRNA SNHG17 releases PGK1 mRNA by adsorbing miR‐628‐5p and activating its pro‐tumour function, further promoting M2‐type macrophage polarisation and tumour progression." (PMID 40579785, 2025). "Subsequently, an animal experiment was conducted to validate the impact of PGK1 on tumorigenesis, wherein tumor growth curves, tumor weights, and Ki-67 (proliferation biomarker) levels were documented." (PMID 38163864, 2024). "Taken together, TRIM55 suppresses tumor growth, migration, and glycolysis by mediating K63-linked ubiquitination of JUP and PGK1, inhibiting the MYC pathway and glycolytic activity." (PMID 39768197, 2024). "PGK1 suppression by miR-16 leads to suppression of tumor growth and metastasis as aerobic glycolysis is a key point in cell proliferation, migration, and tissue invasion." (PMID 38813102, 2024). "Univariate Cox analysis revealed significant correlations between size, tumor stage, vascular invasion, distant metastasis, PGK1 expression, and the prognosis of BLCA patients." (PMID 39315723, 2024). "Previous studies have demonstrated that the glycolytic enzyme phosphoglycerate kinase 1 (PGK1) can promote tumor development." (PMID 39315723, 2024). "The results showed that the effect of circGLIS3 overexpression on tumor progression was abolished by miR-1343-3p mimics, following changes in the PGK1 and PI3K/AKT signaling pathways." (PMID 38459513, 2024). "ATC-CAFs showed high expression levels of genes associated with tumor invasion (MMP14, LOXL2, and PGK1)." (PMID 38478516, 2024). "Studies have revealed a strong correlation between PGK1 overexpression and increased levels of lactate produced by tumor cells." (PMID 38993561, 2024). "Within the tumor microenvironment, PGK1 was observed at heightened levels in both tumor cells and immunosuppressive T cells, where it played a role in fostering an immunosuppressive milieu." (PMID 39712033, 2024). "In consistent with the results from in vitro experiments, FTSJ1 protein expression levels in NSCLC tumor tissues were negatively correlated with that of PGK1." (PMID 39695074, 2024). "PGK1 also can mediate glycolysis, particularly under hypoxic conditions, generating ATP for tumor cell proliferation." (PMID 38247832, 2024). "Inhibition of NEAT1 significantly inhibits tumor growth in mice, but PGK1 can reverse this effect, indicating that NEAT1 overexpression promotes tumor development." (PMID 38967893, 2024). "In the context of solid tumors, particularly under hypoxic conditions within the TME, PGK1-mediated glycolysis supplies essential energy to tumor cells, thereby playing a significant role in the progression of various cancers." (PMID 39590319, 2024). "O‐GlcNAc modification of PGK1 can coordinate glycolysis and tricarboxylic acid cycle, thereby promoting tumor growth." (PMID 39315723, 2024). "It has been reported that PGK1 can promote tumor progression through the PI3K/AKT signaling pathway." (PMID 38459513, 2024). "Elevated NFAT5 expression increases the expression of gluconeogenesis-related genes GLUT1 and PGK1, leading to enhanced aerobic glycolysis, proliferation and tumor metastasis in ICC.METTL3 is a poor prognostic factor for ICC patients." (PMID 39289775, 2024). "The Flag-PGK1-R206K group also showed smaller tumor volumes and tumor weights, and much fewer Ki-67, meR206-PGK1 and pS203-PGK1 positive cells compared with the counterparts in the Flag-PGK1-WT group." (PMID 38402202, 2024). "PGK1 was pivotal in the proliferation of tumor cells, and its downregulation significantly diminished their glycolytic activity, curtailing tumor cell proliferation and tumorigenesis." (PMID 39712033, 2024).
tumor (continued). "The results of multivariate Cox analysis demonstrated that PGK1 expression and tumor stage were independent prognostic factors." (PMID 39315723, 2024). "As a glycolytic enzyme, PGK1 plays a crucial role not only in tumor energy metabolism but also in regulating and expressing multiple cancer proteins." (PMID 38256104, 2024). "The macrophage-regulated tumor cell metabolism mechanism implicates the prospect of a strategy to inhibit the PGK1 phosphorylation." (PMID 37012233, 2023). "E-cadherin induced the redistribution of cytoplasmic β-catenin to the cell membrane, thereby increasing tumor cell-cell adhesion, suggesting that PGK1 is involved in the activation of Wnt signaling and tumor metastasis." (PMID 36807568, 2023). "M2 macrophages secrete a large amount of IL-6, which subsequently enhances 3-phosphoinositide-dependent protein kinase 1 (PDPK1)-mediated phosphoglycerate kinase 1 (PGK1) threonine (T) 243 phosphorylation in tumor cells." (PMID 37012233, 2023). "We expect to delve deeper into the mechanism of MAT inhibiting PGK1 mediated tumor cell metabolism in our next research." (PMID 37524857, 2023). "Collectively, the results showed that miR-4458 played a tumor-inhibiting function in BC cells by binding and inhibiting PGK1." (PMID 36949536, 2023). "Intracellular PGK1 overexpression promoted tumor survival by offering adequate ATP in glycolysis process and reprogramming tumor cell metabolism." (PMID 37408007, 2023). "It was worthwhile emphasizing that the expression level of PGK1 in the SNHG17 sh1 group was lower than that in the control group in both the subcutaneous tumor and the liver model." (PMID 38098044, 2023). "M2 macrophages have shown to secrete interleukin-6 (IL-6), promoting the phosphorylation of Phosphoglycerate Kinase 1 (PGK1) in tumor cells mediated by 3-phosphoinositide-dependent protein kinase 1 (PDPK1)." (PMID 37298093, 2023). "After this, we further measured the expression of the aerobic glycolysis marker named PGK1 in the patients by Immunohistochemistry and also verified the result that PGK1 increased in tumor tissues than in normal tissues." (PMID 37821504, 2023). "In summary, SNHG17 acted as a ceRNA and modulated PGK1 expression by sponging miR-628-5p, enhancing the polarization and pro-tumor activities of M2-like macrophages." (PMID 38098044, 2023). "PGK1 is not only involved in energy production but also plays a crucial role in regulating tumor progression 28-30." (PMID 37670963, 2023). "SMAD4 loss induces the upregulation of PGK1 in PDAC, which enhances glycolysis and aggressive tumor behavior." (PMID 36807568, 2023). "At the same time PGK1 possesses many features of oncogene and promotes tumor growth, as well as cancer cells migration and invasion." (PMID 37449059, 2023). "PGK1 has established a potential tumor promoting role by boosting the HIF-1α expression to stimulate tumor metastasis in BC." (PMID 36949536, 2023). "On the other hand, secreted PGK1 (Phosphoglycerate Kinase 1) has been shown to act on angiostatin levels, resulting in an anti-angiogenic and tumor suppressive function." (PMID 37835519, 2023). "PGK1 is not only involved in energy production but also plays a crucial role in regulating tumor progression 43-46." (PMID 37670963, 2023). "Second, the correlation between PGK1 expression and different subtypes of tumours requires further clarification." (PMID 37723547, 2023). "In recent years, PGK1 proteins have been identified as critical regulators of tumour invasion and metastasis." (PMID 37723547, 2023). "We found that PGK1 was significantly upregulated in tumor tissue compared with their paired normal tissue." (PMID 37670963, 2023). "PGK1 knockdown inhibited tumor growth, resulting in decreased tumor volume and weight compared to control groups." (PMID 36860848, 2023).
tumor (continued). "In summary, as a common target of various miRNAs, PGK1 can serve as a potential biomarker in cancer cells to influence the occurrence and development of tumours by interacting with miRNAs." (PMID 37723547, 2023). "In the current study, increased PGK1 both at the protein and phosphoprotein levels through the tumor progress was observed." (PMID 36966136, 2023). "Some studies have confirmed that long noncoding RNAs (lncRNA) can promote tumor metastasis via PGK1-activated AKT/mTOR pathway." (PMID 37524857, 2023). "The acetylation modification of this site can enhance the activity of the metabolic enzyme PGK1, promote glucose absorption, improve metabolic efficiency, and enhance the tumor-promoting ability of PGK1." (PMID 36684675, 2023). "PGK1 mediates glycolysis, which generates ATP for tumour cells, especially under hypoxic conditions, and it acts as the gatekeeper of the tricarboxylic acid cycle (TCA cycle), which is related to the development and progression of various cancers." (PMID 37723547, 2023). "We found that all Khib sites of PGK1 are upregulation trends in OACC-tumor tissues, including the K323 site (fold change: 1.33)." (PMID 37741973, 2023). "Several studies have revealed that ncRNAs function as tumour regulators by targeting transcription factors, including PGK1." (PMID 37723547, 2023). "We chose PGK1 for further analysis because it is an activator of the Akt pathway and stimulates tumor progression by promoting glycolysis." (PMID 37946295, 2023). "PGK1 is a glycolytic enzyme that catalyzes the conversion of 1,3-diphosphoglycerate to 3-phosphoglycerate and participates in tumor angiogenesis." (PMID 36998462, 2023). "Then we searched online and found the expression of PGK1 is higher in the tumor tissues than the expression in the normal tissues." (PMID 37821504, 2023). "Zhang and colleagues have demonstrated that M2 macrophages enhance 3-phosphoinositide-dependent protein kinase 1 (PDPK1)-mediated phosphoglycerate kinase 1 (PGK1) threonine (T) 243 phosphorylation in tumour cells by secreting IL-6." (PMID 37491279, 2023). "PGK1 T243 phosphorylation mediates macrophage-promoted glycolysis, tumor cell proliferation, and gliomagenesis and correlates with macrophage infiltration, grades, and the prognosis of GBM patients." (PMID 37759870, 2023). "Macrophages promote tumor cell growth and are dependent on PGK1-mediated aerobic glycolysis, which changes PGK1 into a limiting enzyme in cancer cells." (PMID 36755301, 2023). "Consistently, the overexpression of PGK1 protein was confirmed in tumor tissues and cells by western blot." (PMID 36949536, 2023). "Phosphoglycerate kinase 1 (PGK1) is secreted by tumor cells and plays a role in coordinating glycolysis and the TCA cycle during tumorigenesis." (PMID 35252177, 2022). "M2 polarized macrophages secrete IL-6 and phosphorylate PGK1 in glycolysis of tumor cells with malignance and prognosis." (PMID 36077431, 2022). "Macrophages promote tumor growth via regulating tumor cell aerobic glycolysis with PGK1 phosphorylation." (PMID 35586489, 2022). "We further constructed a xenograft tumor model by injecting 786-O-PGK1 cells and 786-O-NC cells to investigate PGK1 influences on carcinogenesis of KIRC in vivo." (PMID 35121728, 2022). "Taken together, PGK1 upregulation is associated with VHL inhibition/mutation and tumor hypoxia in KIRC tissues." (PMID 35121728, 2022). "The genetic modification status of PGK1 was identified in several tumor samples from the TCGA cohorts." (PMID 36358653, 2022). "High intracellular PGK1 expression leads to tumor cell proliferation, while high extracellular PGK1 expression suppresses cancer malignancy through the suppression of angiogenesis." (PMID 36102516, 2022). "Peritoneal metastatic nodules can also migrate to the omentum via chemokine homing from omental adipokines and tumor PGK-1 expression." (PMID 35740519, 2022).